IL5 (interleukin 5)
Diseases named in the same sentence as IL5 in open-access papers (continued):
Sharing a sentence is not in itself a finding about the gene and the disease.
schizophrenia (continued). "Correlation analysis of IL-5, EOS, IgA, disease duration andPANSS scores in patients with schizophrenia (n = 397)." (PMID 40926813, 2025). "IL-5 and EOS are significantly elevated in patients with schizophrenia andexhibit a certain degree of correlation." (PMID 40926813, 2025). "There are no data on the impact of combinations of antipsychotics in TRS patients on other cytokines, e.g., IL-2, IL-4, IL-5, IL-10, IL-12, IL-17, IL-23 and TGF-β1, although their involvement in schizophrenia pathophysiology has been demonstrated." (PMID 39595201, 2024). "The main objective of this study was to assess the effects of ECT on cytokines such as IL-6, IL-12, IL-5, IL-10 and TGF-β1 in patients with treatment-resistant schizophrenia." (PMID 39595201, 2024). "In this work, we found significantly higher serum levels of proinflammatory (IFN-γ, IL-5, IL-6, IL-8, IL-15, and TNF-α) and anti-inflammatory (TGF-α, IL-10, and IL-1RA) cytokines in patients with schizophrenia than in healthy individuals." (PMID 36556337, 2022). "IL-5, EOS, and IgA levels in patients with schizophrenia and inhealthy individuals." (PMID 40926813, 2025). "Therefore, the aim ofthis study was to provide new evidence to enable a better understanding of theroles of IL-5, EOS, and IgA in the pathogenesis and progression of schizophrenia." (PMID 40926813, 2025). "Performances of IL-5 and EOS in schizophrenia identification." (PMID 40926813, 2025). "We found higher TGF-α (p = 0.014), IFN-γ (p = 0.036), IL-5 (p < 0.001), IL-6 (p = 0.047), IL-8 (p = 0.005), IL-10 (p <0.001), IL-15 (p = 0.007), IL-1RA (p = 0.007), and TNF-α (p < 0.001) levels in patients with schizophrenia than in healthy individuals." (PMID 36556337, 2022). "We found higher TGF-α (p = 0.014), IFN-γ (p = 0.036), IL-5 (p < 0.001), IL-6 (p = 0.047), IL-8 (p = 0.005), IL-10 (p < 0.001), IL-15 (p = 0.007), IL-1RA (p = 0.007), and TNF-α (p < 0.001) levels in patients with schizophrenia compared with healthy individuals." (PMID 36556337, 2022). "Studies have shown that patients with schizophrenia exhibitelevated levels of monocytes, neutrophils, and C-reactive protein (CRP).Additionally, various cytokines (e.g., monocyte chemoattractant protein-1,IL-1β, IL-5, IL-6, IL-9 and TNF-α) have been reported to beupregulated in schizophrenia." (PMID 40926813, 2025). "∙ Following two months of treatment, Positive and Negative Symptom Scale (PANSS) scores and IL-5 levels in patients withfirst-episode schizophrenia decreased significantly, suggesting that theelevation in IL-5 is more likely attributable to the disease itself rather thanmedication effects." (PMID 40926813, 2025). "Moreover, differences may exist between first-line and second-linetreatments for schizophrenia, and the effects of various drugs on IL-5, EOS, andIgA levels may not be entirely consistent." (PMID 40926813, 2025). "In patients with schizophrenia, the elevated levels of IL-5 and EOS appear to be disease-related rather than medication-induced, suggesting their potential involvement in the inflammatory pathogenesis of schizophrenia." (PMID 40926813, 2025). "Increased concentration of IL-5 in tears was inversely associated with TBUT, OSDI, and Oxford score in patients with DED, whereas we observed a positive association between IL-5 and TBUT, and a negative correlation between IL-5 and LLT in patients with schizophrenia." (PMID 35223927, 2022).
strongyloidiasis (6 papers, 2006 to 2025). An infection that is caused by nematodes of the genus Strongyloides, most commonly Strongyloides stercoralis, which is a soil-transmitted helminth, and which is characterized by a variety of gastrointestinal, dermatologic, and, occasionally, pulmonary manifestations. "This was associated with a blunted antigen-specific IL-5 response and lower eosinophil counts compared to patients with only chronic strongyloidiasis." (PMID 31170141, 2019). "The increased number of Tregs is associated with a blunted antigen-driven IL-5 expression, and significantly lower peripheral eosinophil counts in HTLV-1 co-infected patients compared with patients with only Strongyloides infection." (PMID 31170141, 2019). "Blood analysis, flow cytometry and interleukin-5 responses to Strongyloides stercoralis larval antigens A peripheral blood sample was obtained at enrollment from all strongyloidiasis patients." (PMID 19513105, 2009). "IL-5 is a key host molecule in stimulating eosinophil production and activation, and Strongyloides stercoralis antigen-specific IL-5 responses were reduced in strongyloidiasis/HTLV-1 co-infected patients." (PMID 19513105, 2009). "Strongyloides antigen-specific IL-5 responses were reduced in strongyloidiasis/HTLV-1 co-infected patients (5.0 vs. 187.5 pg/ml, p = 0.03, Mann-Whitney test)." (PMID 19513105, 2009). "PBMC's from strongyloidiasis patients produced IL-5 in response to S. stercoralis infective stage larvae crude antigen." (PMID 19513105, 2009). "Type 2 T helper (Th2) cells that stimulate eosinophils, IgE production, mast cells, and goblet cells by producing IL-4, IL-5, IL-9, IL-10 and IL-13, are important in the defense against strongyloides infection." (PMID 16734908, 2006). "However, higher values of conventional Th2 cells (IL-4+, IL-13+ or IL-5+) correlated with increased Th2/1 hybrid cell frequencies co-expressing IFN-γ and the respective Th2 cytokines (p < 0.0001) irrespective of the Strongyloides infection status." (PMID 28676845, 2017).
tetanus (6 papers, 2010 to 2017). A serious infectious disorder that follows wound contamination by the Gram-positive bacterium Clostridium tetani. "Infant malaria is associated with lower IFNγ, IL5 and IL13 (i.e. Th1) responses to both BCG and tetanus immunisation." (PMID 29124321, 2017). "Generally, more tetanus- than diphtheria-specific T cells were detected prior to and after the vaccination and the number of IL-5 secreting diphtheria-specific T cells was generally low." (PMID 24349407, 2013). "Tetanus immunisation during pregnancy was associated with higher infant responses to TT; maternal BCG scar (from past immunisation) with lower infant IL-5 and IL-13 responses to cCFP." (PMID 21040693, 2010). "Tetanus immunisation during pregnancy was associated with enhanced IFN-γ, IL-13 and (to some extent) IL-5 responses following tetanus immunisation of the offspring." (PMID 21040693, 2010). "An increasing number of doses of maternal tetanus immunisation during the pregnancy was associated with increased infant IFN-γ (aGMR 1.44 (1.16, 1.79)) and IL-13 (1.22 (1.01, 1.46)), and a weak increase in IL-5 (aGMR 1.19 (0.97, 1.44)) responses to TT." (PMID 21040693, 2010). "The proportion of children for whom positive responses to cCFP, antigen 85 and tetanus toxoid were detected varied by cytokine: for cCFP, 86%, 48%, 71% and 90% of infants had positive responses to IFN-γ, IL-5, IL-13 and IL-10, respectively." (PMID 23236367, 2012). "Of note, only maternal Mansonella perstans infection was associated with significantly higher IL10 responses to BCG and tetanus immunisation but with no reduction in IFNγ, IL5 and IL13 responses." (PMID 29124321, 2017). "While antigen-specific IFN- γ and IL-5 production did not correlate with antibody concentrations for tetanus (p=0.258 and p=0.065), there was a correlation between antibody concentrations and IL-5 (p=0.002), but not IFN-γ production (p=0.036) for diphtheria." (PMID 24349407, 2013).
type 2 diabetes (6 papers, 2012 to 2025). "Multiple taxa priorly associated with cardiovascular disease and type 2 diabetes were linked with specific cytokines (e.g., greater Enterococcus and IL-5 and TNF-a, lower Coprococcus and TNF-a), possibly indicating a shift to a more inflammatory state." (PMID 36609477, 2023).
ZIKV infection (6 papers, 2017 to 2026). "Other studies have also reported a positive correlation between IL‐5 levels and headaches during ZIKV infection." (PMID 41556482, 2026). "These cytokines have diverse functional patterns such as Th1 (IFN-γ), Th2 (IL-5), and Th9 (IL-9) cells, suggesting the activation of these T helper lymphocyte subsets in acute ZIKV infection." (PMID 29774022, 2018). "ZIKV infection triggered the upregulation of multiple cytokines in humans during acute phase of infection that we were able to characterize by Luminex assay, including IP-10, IL-5, GM-CSF, TNF-α, IL-15, IL-10, MIP-1α, IFN-γ, IL-6, IL-1RA, IL-2, MIG, IFN-α, IL-2R, and IL-4." (PMID 30333476, 2018). "Cytokines and chemokines with higher levels during acute ZIKV infection were IP-10, RANTES, IFN-γ, IL-9, IL-7, IL-1ra, and IL-5, involving innate and adaptive immune responses." (PMID 29774022, 2018). "In our study, levels of several immune markers, such as IFN-α, IL-12, IL-6, IL-17, IL-10, IL-5, IL-2R, ST2/IL-1R4, CCL2, CCL3, CXCL9, M-CSF and E-Selectin, were significantly higher in presymptomatic/asymptomatic ZIKV infection (A-ZIKV group) when compared to the NI control group." (PMID 31748599, 2019). "In this more stringent analysis, the frequency difference of IFN-γ was no longer significant, whereas IL-5 and IL-7 showed higher frequency of detection in acute ZIKV infection in relation to the normal physiological state." (PMID 29774022, 2018). "We also observed no production of either the Th2 cytokine IL-5 or the Th17 cytokine IL-17, further confirming that ZIKV infection induces a Th1-polarized response." (PMID 28231312, 2017).
allergic conjunctivitis (5 papers, 2011 to 2023). "Immunohistochemistry, real-time PCR, and Luminex technology were used to measure the expression of TSLP, IL-4, IL-5, and IL-13 in the tears and conjunctival cell of the normal population and patients with three types of allergic conjunctivitis." (PMID 27504196, 2016). "The tear TSLP, IL-4, IL-5, and IL-13 expression levels in different types of allergic conjunctivitis were found elevated to varying degrees in the VKC, SAC, and PAC compared with the control group; the differences were statistically significant (P < 0.001)." (PMID 27504196, 2016). "The present study sought to investigate the expression of TSLP and its downstream molecules IL-4, IL-13, and IL-5 in the conjunctival tissue of patients with allergic conjunctivitis and tear." (PMID 27504196, 2016). "Immunohistochemical staining confirmed an increase in TSLP, IL-4, IL-5, and IL-13 production in the eyes with various types of allergic conjunctivitis." (PMID 27504196, 2016). "A study reported increases in IL-1β, IL-2, IL-5, IL-6, IL-12, IL-13, in seasonal allergic conjunctivitis (SAC), vernal keratoconjunctivitis (VKC) and atopic keratoconjunctivitis (AKC), while IL-4, IFN-γ and IL-10 levels were increased in SAC and VKC compared to controls." (PMID 21298010, 2011). "The conjunctival tissues of various types of allergic conjunctivitis displayed stronger TSLP, IL-4, IL-5, and IL-13 staining throughout the entire epithelium than did those of normal controls." (PMID 27504196, 2016). "Tanaka and Alfonso demonstrated that Sema3a suppressed the release of Th2-related cytokines (IL-5, IL-13 and IL-4) and inflammatory cytokines (IFN-α, IL-17 and TNF-α) but increased levels of the cytokine IL-10 in experimental allergic conjunctivitis and autoimmune arthritis models." (PMID 29975739, 2018). "We conclude that the high levels of IL4, IL5, and IL13 that characterize allergic conjunctivitis could be the reason for higher numbers of goblet cells and mucin overproduction found in this condition." (PMID 30111832, 2018). "The purpose of this study is to determine whether IL4, IL5 and IL13, players in allergic conjunctivitis, directly regulate mucin production in rat conjunctival goblet cells." (PMID 30111832, 2018). "In light of our results, the high levels of IL4, IL5, and IL13 that characterize allergic conjunctivitis could be the reason for the increased number of goblet cells and could have a role in the mucin overproduction found in this pathological condition." (PMID 30111832, 2018).
Cirrhosis (5 papers, 2019 to 2025). A chronic disorder of the liver in which liver tissue becomes scarred and is partially replaced by regenerative nodules and fibrotic tissue resulting in loss of liver function. "Conversely, cirrhosis was linked to decreased levels of IL-2 receptor alpha (IL-2RA), IL-5, IL-7, and tumor necrosis factor beta (TNF-β)." (PMID 39457577, 2024). "Other cytokine combinations, such as IL-5 and GM-CSF, were found to be new potential therapeutic tools, and highlighted the ability of the subset of cytokine-releasing cells of the peritoneal cavity to counteract cirrhosis progression leading to HCC development." (PMID 37686245, 2023).
Cognitive impairment (5 papers, 2021 to 2025). Abnormal cognition is characterized by deficits in thinking, reasoning, or remembering. "Generally, the evidence suggests that IL-5 is linked to cognitive impairment in individuals with T2DM." (PMID 39347908, 2025). "One study found that elevated IL-5 levels in T2D patients were significantly associated with slower information processing speed in individuals with mild cognitive impairment (MCI), suggesting a link between IL-5 and neuroinflammation in metabolic disease." (PMID 40804870, 2025). "Through clinical experiments, we verified the correlation between IL-5 and cognitive impairment, and evaluated the diagnostic value of IL-5 for MCI in patients with T2DM." (PMID 39347908, 2025). "We found that patients with impaired cognition had significantly elevated levels of IL-5 compared to those with normal cognition (P = 0.001)." (PMID 39347908, 2025). "In the context of cognitive deficits after TBI, we found that several inflammations and immune-related genes (Mterf1a, Trp73, Cd3d, Dll1, and Il5) had abnormal expression levels lncRNAs may potentially target." (PMID 35311004, 2022). "Although the level of sTNFRII was found to be associated with subjective cognitive complaints in BC patients with or without chemotherapy, no previous reports were found in the associations of IL-5 or IL13 and subjective cognitive impairments." (PMID 34073990, 2021).
coronary artery disease (5 papers, 2016 to 2024). "In this study we aimed to identify genetic variants associated with IL-5 concentrations and apply a Mendelian randomisation approach to assess IL-5 levels for causal effect on intima-media thickness in a European population at high risk of coronary artery disease." (PMID 26821299, 2016). "In addition to elevation of the proinflammatory cytokines IL1β, TNF-α and IL-6, exercise may reduce C-reactive proteins in patients with coronary arteriosclerosis and Type II T helper cytokines (IL-5 and IL-13) in asthmatic BALB/c mice." (PMID 32778140, 2020). "For example, an observational study reported a negative association between eosinophils and coronary heart disease (CHD), and higher levels of IL-5 were linked to reduced subclinical atherosclerosis." (PMID 39394116, 2024).
cutaneous leishmaniasis (5 papers, 2006 to 2023). Leishmaniasis affecting the skin. "The levels of IL-5 and IL-10 production by PBMC were very low and similar in PBMCs from both disseminated leishmaniasis and cutaneous leishmaniasis patients." (PMID 16638143, 2006).
dengue (5 papers, 2008 to 2026). "In a subsequent analysis comparing mild dengue with the combined DFWS/SD group, significantly higher exosomal levels of IL-1β, IL-5, IL-10, IL-12, IL-13, and TNF-α were observed in the DFWS/SD group (all p < 0.05)." (PMID 41993203, 2026). "Plasma concentrations of n = 43/48 markers were found to be significantly different between dengue patients and healthy controls, except for n = 5/48 markers including TRAIL (p = 0.082), TNF‐beta (p = 0.991), GM‐CSF (p = 0.405), IL‐5 (p = 0.078), and IL‐7 (p = 0.051)." (PMID 40704559, 2025). "By using multiplex immunoassay, we compared host cytokine profiles between acute CHIKV and DENV infections by analysing serum cytokine levels of IL-1α, IL-4, IL-5, IL-8, IL-13, RANTES, MCP-3, eotaxin, PDGF-AB/BB, and FGF-2 from the sera of acute chikungunya and dengue fever patients." (PMID 34215212, 2021).
eosinophilic pneumonia (5 papers, 2019 to 2025). An inflammatory lung disorder characterized by an increased number of eosinophils in the lungs. "IL-5 is a central mediator of eosinophil maturation and survival and eosinophilic pneumonia can occur consequent to viral infection." (PMID 35145069, 2022). "The main mechanism of acute eosinophilic pneumonia has been elucidated to be due to pro-inflammatory cytokines such as IL-5, IL-6, IL-7, and tumor necrosis factor." (PMID 32366239, 2020). "In contrast, IL-5 was stable in patients who did not develop dupilumab-related eosinophilic pneumonia." (PMID 36551171, 2022).
epilepsy (5 papers, 2015 to 2025). A brain disorder characterized by episodes of abnormally increased neuronal discharge resulting in transient episodes of sensory or motor neurological dysfunction, or psychic dysfunction. "Epilepsy was associated with IL-5 (r = 0.347, P = 0.0020), IL-10 (r = 0.328, P = 0.0036), IL-12p70 (r = 0.370, P = 0.0001), IL-13 (r = 0.346, P = 0.0021), and F2-IsoPs (r = 0.536, P < 0.0001)." (PMID 26236424, 2015). "To investigate the underlying mechanisms, we performed bioinformatic analyses to identify critical genes that might be associated with epilepsy through IL-5." (PMID 39259090, 2024). "Previous observational studies have shown a significant increase in IL-5 in patients with epilepsy (especially in those with drug-resistant epilepsy)." (PMID 39259090, 2024). "However, valproates increase IL-1, IL-6, and IL-5 levels in patients with epilepsy." (PMID 40217882, 2025).
experimental autoimmune encephalomyelitis (5 papers, 2010 to 2022). An autoimmune demyelinating disease of the central nervous system that is produced experimentally in animals by the injection of homogenized brain or spinal cord in Freund's adjuvant. "It has been reported that N. brasiliensis infection protects against experimental autoimmune encephalomyelitis (EAE) via increased IL-5 levels and subsequent increases in eosinophils and CD4+CD25+ Tregs." (PMID 35625566, 2022).
fungal infection (5 papers, 2017 to 2025). "Anti-inflammatory cytokines such as IL-3, IL-4, IL-5, IL-9, IL-10, and IL-13 were also induced within 3 h of fungal infection in all three groups of mice and remained high up to the 7th day period." (PMID 38783167, 2024). "Cytokines involved in granuloma development, primarily IL-33, IL-5, and IL-13 were evaluated considering previous data on fungal infections." (PMID 34829225, 2021). "Meanwhile, anti-inflammatory cytokine IL-10 and type 2 cytokines (IL-4, IL-5, and IL-13) were similar in the WT or CD146 KO mice with fungal infection." (PMID 33537006, 2020).
Giardia-infection (5 papers, 2018 to 2023). "Although the Th1 cytokine IFN-γ and the Th2 cytokines IL-4 and IL-5 have been shown to be elevated in Giardia-infection models, both IFN-γ-deficient and IL-4-deficient mice can still eliminate Giardia, suggesting that the Th1 and Th2 responses are not essential for clearance." (PMID 32283818, 2020). "Proinflammatory chemokines, including TNF-α, and B lymphocyte activating interleukins, such as IL-4 and IL-5 belong to the chemokine profile described in Giardia infection." (PMID 34778111, 2021). "First we studied cytokines that earlier have been shown to be up-regulated during Giardia infections in mice, i.e. IL-1, IL-2, IL-4, IL-5, IL-9, IL-10, IL-12, IL-17a, IL-17c, IFN-γ, TGF-β, and TNF-α." (PMID 34335577, 2021). "Untreated Giardia-infection may regulate innate and adaptive immune responses mediated by Th17 CD4+T cells and induction of Th1, Th2 and Th17 cytokines, including IL-2, IL-5, IL-6, IL-8, IL-12, IL-13, IL-23, IFN-γ and TNF-α." (PMID 30412580, 2018).